RBP3 (retinol binding protein 3)
Description:
Mediates the transport of 11-cis- and all-trans-retinoids between the retinal pigment epithelium (RPE) and photoreceptors, facilitating retinoid exchange required for the visual cycle.
Synonyms: IRBP; D10S64; D10S65; D10S66; RP66; RBPI
Tractability: Antibody: its Gene Ontology location is reachable by antibodies, with high confidence; UniProt places it where antibodies can reach, with medium confidence; UniProt predicts a signal peptide or a membrane-spanning region.
Gene: Protein-coding gene on chromosome 10 (47,348,363 to 47,357,881, forward strand). Ensembl gene ENSG00000265203.
Subcellular location: Secreted, extracellular space, extracellular matrix, interphotoreceptor matrix
Pathways (Reactome):
Sensory Perception: The canonical retinoid cycle in rods (twilight vision); The retinoid cycle in cones (daylight vision)
Gene Ontology:
Molecular function: protein binding; retinoid binding; retinol binding; serine-type peptidase activity
Biological process: lipid metabolic process; retinoid metabolic process; visual perception; proteolysis
Cellular component: extracellular region; extracellular vesicle; cone matrix sheath; interphotoreceptor matrix
Genetic constraint (gnomAD): Loss-of-function variants: 52 observed, 68.39 expected, observed/expected ratio (o/e) 0.76, 90% interval 0.61 to 0.96. The upper end of that interval is the gene's LOEUF score, 0.96, which puts it in group 4 of 6, group 1 being the genes least tolerant of losing a copy. Missense variants: 1,712 observed, 1,737.8 expected, observed/expected ratio (o/e) 0.99, 90% interval 0.95 to 1.02. Synonymous variants: 828 observed, 765.22 expected, observed/expected ratio (o/e) 1.08, 90% interval 1.02 to 1.15.
Homologues: Orthologues: chimpanzee RBP3 (99% identical), macaque RBP3 (98% identical), rabbit RBP3 (85% identical), rat Rbp3 (85% identical), mouse Rbp3 (84% identical), dog RBP3 (84% identical), pig RBP3 (84% identical), guinea pig RBP3 (82% identical), tropical clawed frog rbp3 (58% identical), zebrafish rbp3 (20% identical).
Diseases named in the same sentence as RBP3 in open-access papers:
RBP3 is named in the same sentence as 53 diseases in open-access papers, as found by Europe PMC text mining. Sharing a sentence is not in itself a finding about the gene and the disease. The quoted sentences say what the papers report.
uveitis (19 papers, 2012 to 2025). An inflammatory process affecting a part of or the entire uvea. "High titers of autoantibodies directed against photoreceptor-specific nuclear receptor and retinol-binding protein 3 were more common in patients with presumed (n)pAIR compared to uveitis (p = 0.015 and p = 0.018, respectively)." (PMID 27930731, 2016). "The R161H– Rbp3–/– mice didnot developed uveitis, due to lack of target antigen in their eyes." (PMID 34840686, 2021). "High titre autoantibodies to photoreceptor-specific nuclear receptor and retinol-binding protein 3 were more prevalent in patients with (n)pAIR than in patients with uveitis (p = 0.015 and p = 0.018, respectively; p-values were not significant after applying correction for multiple testing)." (PMID 27930731, 2016).
diabetic retinopathy (7 papers, 2023 to 2025). "A higher level of RBP3 in the vitreous was associated with less severe diabetic retinopathy and a reduced risk of developing proliferative diabetic retinopathy (PDR) in participants of the Medalist Study." (PMID 37446043, 2023). "Recently the levels of RBP3 have been linked to the development of diabetic retinopathy." (PMID 41222740, 2025). "The antioxidant component of resilience has been noted by other groups reporting that expression of RBP3 (retinol-binding protein 3), an antioxidant, is elevated in patients who are resistant to diabetic retinopathy." (PMID 38338889, 2024). "Interestingly, RBP3 expression was inversely correlated with diabetic retinopathy, suggesting a protective effect against the disease potentially through interaction with vascular endothelial growth factor A (VEGF)." (PMID 40076480, 2025).
retinal degeneration (7 papers, 2018 to 2025). Degeneration of the retina. "High myopia appears to be a hallmark of the RBP3-retinal degeneration, and targeted screening of this gene may be considered in patients with high myopia and retinal dystrophy, if not already included in panel screening." (PMID 37806543, 2024). "Interestingly, loss-of-function mutations in RBP3 result in retinal degeneration associated with retinitis pigmentosa." (PMID 32345717, 2020). "Interestingly, RPB3 is critical for the visual cycle, and it has been reported that Rbp3 mRNA levels are reduced in the light-induced retinal degeneration rat model." (PMID 40832922, 2025). "Furthermore, and perhaps indicative of RBP3 as a marker of early disease states, the mouse model rd12, used in retinal degeneration studies, shows downregulation of the RBP3 protein." (PMID 36901838, 2023). "Lastly, we profiled gene expression between AdipoR1 WT, heterozygous (HET), and KO animals and found that the interphotoreceptor retinoid-binding protein (IRBP, aka RBP3) was strongly upregulated in KO eyes prior to retinal degeneration, suggesting retinoid metabolism dysfunction." (PMID 30254279, 2018). "Finally, as substrate processing may define the molecular basis for HTRA1-induced retinal degeneration, we initiated a proteomics approach and identified the visual cycle key player RBP3 as a disease-relevant HTRA1 substrate in the retina." (PMID 40832922, 2025).
myopia (6 papers, 2020 to 2025). "All 8 children had high myopia, highlighting RBP3-variants as a rare cause of retinal dystrophy and high myopia." (PMID 37806543, 2024). "Considering the association of RBP3 with myopia, the available data identify several mutations that suggest a loss of function may be the genetic mechanism of RBP3-related myopia, as it is for DR and RP." (PMID 39837501, 2025). "Furthermore, all eight affected patients in these studies had high myopia, thus suggesting an association between RBP3-related retinopathy and high myopia." (PMID 41153400, 2025). "Some identified variants showed precise scaling in corneal curvature and eye elongation (i.e. axial length) to maintain eyes in emmetropia (i.e. HDAC11/FBLN2 rs2630445, RBP3 rs11204213); others exhibited association with myopia with little pleiotropic effects on eye elongation." (PMID 32193507, 2020). "RBP3-retinopathy is a disease characterized by early onset, slow progression over decades, high myopia, and a variable retinal function phenotype." (PMID 37806543, 2024). "RBP3-retinopathy is a disease characterized by early onset, slow progression over decades, and high myopia." (PMID 37806543, 2024). "Malfunctions of RBP3 are believed to contribute to the pathologies of several retinal diseases, including diabetic retinopathy (DR), retinitis pigmentosa (RP), pan-retinal degeneration and exaggerated eye growth and myopia." (PMID 39837501, 2025). "RBP3-related disease should be considered in children with high myopia and retinal dystrophy." (PMID 37806543, 2024). "Lack of Rbp3 in mice caused excessive eye growth and myopia." (PMID 39607017, 2024). "RBP3-related disease should be considered in adults and children with high myopia and retinal dystrophy, with or without nyctalopia." (PMID 37806543, 2024). "RBP3 screening in young patients with pathologic myopia, with or without retinal dystrophy, may further help to estimate the prevalence of the disease, as well as contribute to improved understanding of the disease phenotype and natural history by identifying more affected individuals." (PMID 37806543, 2024).
retinitis pigmentosa (6 papers, 2017 to 2025). Retinitis pigmentosa (RP) is an inherited retinal dystrophy leading to progressive loss of the photoreceptors and retinal pigment epithelium and resulting in blindness usually after several decades. "Mutations in RBP3 are linked to a group of inherited retinal dystrophies, including retinitis pigmentosa (RP) and cone-rod dystrophy." (PMID 40895869, 2025). "Furthermore, RBP3 is a glycoprotein expressed in the interphotoreceptor matrix of the retina; it is also associated with retinitis pigmentosa." (PMID 28484645, 2017). "Our proteomic data showed significant changes in the levels of proteins for retinitis pigmentosa (RPE65, RP2, MERTK, and RBP3), X-linked retinoschisis (RS1), CRB1-retinal dystrophy (CRB1), Usher syndrome (PCDH15), and Leber congenital amaurosis (RD3 and KCNJ13)." (PMID 36139394, 2022).
retinal dystrophies (5 papers, 2021 to 2025). "The limitation of this case report lies in its focus on a single patient due to the low incidence of mutations in the RBP3 gene, and further studies with larger cohorts are needed to better understand the full spectrum of RBP3-related retinal dystrophies." (PMID 40895869, 2025). "This case highlights the importance of genetic testing in diagnosing retinal dystrophies, as well as the need for further studies to explore the full spectrum of RBP3-related retinal conditions." (PMID 40895869, 2025). "Future investigations, including genetic analysis of family members, would enhance understanding of RBP3-related retinal dystrophies." (PMID 40895869, 2025). "The confirmed genetic diagnosis in the retinal dystrophy group included RP in three (AGBL5, RBP3, and PRPF8), Leber congenital amaurosis in one (RPE65) and gyrate atrophy in one (OAT)." (PMID 33494148, 2021).
Autoimmunity (4 papers, 2014 to 2025). The occurrence of an immune reaction against the organism's own cells or tissues. "Both elevated seroreactivity to RBP3 and RLBP1 in AMD patients suggests that the inflammation, in particular, autoimmunity, is strongly associated with the pathogenesis of the disease." (PMID 25488058, 2014).
Hyperglycemia (4 papers, 2023 to 2025). An increased concentration of glucose in the blood. "One such factor identified in these resilient individuals is retinol-binding protein 3 (RBP3), which reduces glucose uptake in photoreceptors and attenuates inflammatory signaling, thereby limiting hyperglycemia-induced retinal damage." (PMID 40508021, 2025).
retinoblastoma (4 papers, 2012 to 2026). A malignant tumor that originates in the nuclear layer of the retina. "Expression of Rgr is typically linked to RPE and Muller cells, Abca4 to photoreceptors and Rbp3 to photoreceptor and retinoblastoma cells (Entrez)." (PMID 32655363, 2020). "Together, these findings demonstrate that cfRNA- and ctcRNA-based liquid biopsy using CRX and RBP3 enables sensitive and dynamic detection of disseminated retinoblastoma, particularly in bone marrow, and supports its potential utility for MRD monitoring." (PMID 42196162, 2026). "Here, we evaluate the feasibility of cell-free RNA (cfRNA)- and circulating tumor cell RNA (ctcRNA)-based liquid biopsy for the sensitive detection of disseminated retinoblastoma using digital PCR (dPCR) targeting the retina-specific markers CRX and RBP3." (PMID 42196162, 2026).
cataract (2 papers, 2021 to 2022). Partial or complete opacity of the crystalline lens of one or both eyes that decreases visual acuity and eventually results in blindness. "For example, in the case of Patient 12-1, who presented with cataracts but was subsequently found to have RP likely to be caused by a mutation in RBP3 gene, which is not included in routine cataract gene panels." (PMID 33494148, 2021).
glaucoma (2 papers, 2016 to 2019). Increased pressure in the eyeball due to obstruction of the outflow of aqueous humor. "In contrast, retinal dehydrogenase 1 (RALDH 1), retinol-binding protein 3 (IRBP) and vesicle-associated membrane protein-associated protein B/C, showed significant level enhancement referring to glaucoma (p < 0.05)." (PMID 27425789, 2016). "Also, retinol-binding protein 3, retinal dehydrogenase 2 and retinoic acid receptor responder protein 2 could be identified, which is interesting since TM expression of glaucoma-related myocilin was demonstrated to be regulated by retinoic acid." (PMID 31121981, 2019).
autosomal recessive retinitis pigmentosa (1 paper, 2011). Autosomal recessive retinitis pigmentosa (RP) is an autosomally recessive inherited retinal dystrophy leading to progressive loss of the photoreceptors and retinal pigment epithelium and resulting in blindness usually after several decades. "We observed significant down-regulation of RBP3 in NOD.NON-H2-nb1 (-7.9 fold, p<3.2×10−9), a gene in which mutations have been associated with autosomal recessive retinitis pigmentosa." (PMID 21779340, 2011).
macular degeneration (1 paper, 2006). Loss of vision in the central portion of the retina (macula), secondary to retinal degeneration. "This group included rod specific genes Rbp3, Elovl4, and Abca4, the last two of which have been associated with macular degeneration in humans." (PMID 17044933, 2006).
primary congenital glaucoma (1 paper, 2022). "Significantly lower levels of TTR and RBP3 were measured in the aqueous humor of primary congenital glaucoma patients." (PMID 35682657, 2022).
type 2 diabetes (1 paper, 2022). "Using pharmacophore target analysis in a network pharmacology approach, we identified five potential target genes for celastrol in the treatment of type 2 diabetes, including RBP3, BMP7, S100A11, HBB and IQUB." (PMID 36339449, 2022).
retinopathy (3 papers, 2024 to 2025). "Anneke I. den Hollander first described the association of the retinol-binding protein 3 (RBP3) gene with retinopathies in 2009." (PMID 40895869, 2025). "Presumably, loss of function is the genetic mechanism of RBP3-retinopathy, given the confirmed autosomal recessive inheritance and the phenotypic features of irbp−/− KO mouse (photoreceptor abnormality) and irbp−/+ heterozygote mouse (no changes)." (PMID 37806543, 2024). "Further research is needed to clarify genotype-phenotype correlations in RBP3-related retinopathies." (PMID 40895869, 2025). "This study details the clinical and functional phenotype of RBP3-retinopathy in the largest cohort reported to date." (PMID 37806543, 2024). "Multi-center international, retrospective, case series of adults and children, with moleculraly confirmed RBP3-asociated retinopathy." (PMID 37806543, 2024). "The natural history and visual prognosis of RBP3-retinopathy is poorly understood, and informed patient management is limited by the rarity of the disease and related literature." (PMID 37806543, 2024). "The current study describes the genetic, clinical, and imaging characteristics of 12 patients with molecularly confirmed RBP3-retinopathy, including cross-sectional and longitudinal analysis." (PMID 37806543, 2024). "Despite these limitations, this study provides the most comprehensive analysis to date of the genetic, structural, functional, and clinical characteristics RBP3-retinopathy, including insight into natural history." (PMID 37806543, 2024). "This study details the clinical and electrophysiological phenotype of RBP3 retinopathy in the largest cohort reported to date." (PMID 37806543, 2024). "RBP3-retinopathy has been reported in only 3 families, with a total of 8 affected members." (PMID 37806543, 2024). "These suggest both loss of function and gain of a harmful function, which may occur in RBP3-retinopathy." (PMID 37806543, 2024).
tumor (3 papers, 2021 to 2026). "RBP3, associated with the CM of myeloid cells and phagocytes, and C1QTNF1, associated with the activation of platelets, played key roles towards metastasis in the tumor microenvironment." (PMID 34068397, 2021).
RBP3 also shares sentences with these, for which no sentence is quoted: autoimmune uveitis (10 papers); retinal diseases (5); autoimmune disease (2); cancer (2); Leber congenital amaurosis (2); retinal tumor (2); X-linked retinoschisis (2); autoimmune myocarditis (1); bacterial infections (1); Behcet disease (1); breast carcinoma (1); cervical squamous cell carcinoma (1); diabetes (1); endocervical adenocarcinoma (1); gastric cancer (1); gyrate atrophy (1); Hepatitis (1); leukemia (1); lung squamous cell carcinoma (1); macular telangiectasia type 2 (1); melanoma (1); microphthalmia (1); myopathy (1); nyctalopia (1); Obesity (1); ocular onchocerciasis (1); oral carcinoma (1); papilledema (1); pheochromocytoma and paraganglioma (1); proliferative diabetic retinopathy (1).
A further 6 diseases each share a sentence with RBP3 in 1 paper.